MPO (myeloperoxidase)
Diseases named in the same sentence as MPO in open-access papers (continued):
Sharing a sentence is not in itself a finding about the gene and the disease.
Takayasu arteritis (2 papers, 2023 to 2024). A rare inflammatory large-vessel vasculitis primarily affecting the aorta and its major branches, but also other large vessels, causing stenosis, occlusion, or aneurysm. "The coexistence of aPL antibodies and dual specificity for MPO and PR3 in a patient diagnosed with Takayasu arteritis is unusual and poses a diagnostic challenge." (PMID 37893200, 2023).
thrombotic disease (2 papers, 2020). The formation of a blood clot in the lumen of a vessel or heart chamber; causes include coagulation disorders and vascular endothelial injury. "Contrary to this, however, a recent study shows that MPO inhibits phospholipid-dependent coagulation, while acquired neutrophil MPO deficiency in man is associated with thrombotic disease." (PMID 32168908, 2020). "Few studies have been conducted to assess OxS in thrombotic diseases of the venous circulation, although high levels of myeloperoxidase, MDA, and 4-HNE have been demonstrated in VTE." (PMID 33276677, 2020).
triple-negative breast carcinoma (2 papers, 2023 to 2025). An invasive breast carcinoma which is negative for expression of estrogen receptor (ER), progesterone receptor (PR), and human epidermal growth factor receptor 2 (HER2). "The triple-negative breast cancer cell lines MDA-MB-231 and HCC1937 were found to induce an upregulation of MPO-DNA, a marker for NETs formation." (PMID 40148973, 2025).
unstable angina pectoris (2 papers, 2010 to 2017). "Leukocyte counts and concentrations of MPO were significantly increased in patients with unstable angina pectoris compared with controls." (PMID 21188207, 2010). "Moreover, apoA-I was also found over-abundant in advanced plaques from unstable angina pectoris patients and co-localized with MPO, which raised an interesting question-whether MPO weakens plaque stability in advanced atherosclerotic lesions through oxidation of HDL." (PMID 28069011, 2017).
varicocele (2 papers, 2021 to 2024). A condition characterized by the dilated tortuous veins of the spermatic cord with a marked left-sided predominance. "Finelli and colleagues reported that patients with varicoceles differentially expressed several key proteins (e.g., fatty acid synthase, myeloperoxidase, or mitochondrial aconitate hydratase) specifically associated with DNA repair." (PMID 38392299, 2024). "In silico analysis identified two additional proteins (NUP93 and MPO) that were predicted to be significantly altered in varicocele sperm." (PMID 34975746, 2021). "In particular, the analysis showed 2 (FASN, MPO) and 3 (ACO2, NUP93, and PSMD14) proteins, which were significantly over- and under-expressed, respectively (P <0.03) in varicocele samples and reported to be involved in DNA repair function." (PMID 34975746, 2021). "In our study, the predicted overexpression of MPO may be related to reduced NER activity and increased varicocele-induced inflammation." (PMID 34975746, 2021).
venous thromboembolism (2 papers, 2020 to 2025). Occlusion of the lumen of a vein by a thrombus that has migrated from a distal site via the blood stream. "We quantified three markers of neutrophil activation (cell-free DNA, calprotectin, and myeloperoxidase) in 253 patients with venous thromboembolism (VTE) in a stable phase (192 lower extremity VTE and 61 splanchnic vein thrombosis) and in 249 healthy controls." (PMID 32781781, 2020).
ventricular dilatation (2 papers, 2015 to 2019). "In post myocardial infarcted MPO−/− knockout mice, thinning of the ventricular walls was reduced and ventricular dilatation was attenuated." (PMID 31822739, 2019). "Newborns with hyperEPO only were not at significantly different risk of ventriculomegaly, whereas those with ISSI only (MPO, IL-1 β, IL-6, TNF- α, IL-8, MCP-1, VEGF, VEGF-R1, orange) were 2–5 times more likely to have ventriculomegaly than children without either hyperEPO or ISSI." (PMID 25793991, 2015).
viral acute hepatitis (2 papers, 2021 to 2024). "Patients with an underlying NASH had significantly higher H3Cit-DNA and MPO-DNA levels compared to those with viral hepatitis." (PMID 34504150, 2021).
viral pneumonia (2 papers, 2025). Inflammation of the lung parenchyma that is caused by a viral infection. "The viral pneumonia patients showed increased levels of CitH3, MPO, NE, and LL37 compared to healthy individuals." (PMID 40659620, 2025). "The co-expression of MPO and Cit-H3 (markers for NETs) was lower in the bronchi and alveoli of STING-KO mice infected with PR8 than in those of the counterpart WT mice, indicating that the activation of STING promotes the formation of NETs in viral pneumonia." (PMID 40666504, 2025).
vitamin D deficiency (2 papers, 2022 to 2023). A nutritional condition produced by a deficiency of VITAMIN D in the diet, insufficient production of vitamin D in the skin, inadequate absorption of vitamin D from the diet, or abnormal conversion of vitamin D to its bioactive metabolites. "As vitamin D deficiency improved (from severely deficient to insufficient and sufficient 25(OH)D groups), MPO showed a decreasing trend in both men and women (P for trend < 0.0001)." (PMID 35983482, 2022). "Of note, the potential resulting from vitamin D supplementation would bias toward to the null and thus result in an underestimation of the association between MPO and vitamin D deficiency/insufficiency." (PMID 35983482, 2022). "To assess unmeasured confounding by calculating E value, we found that confounders having a relative risk association = 2.94 with both elevated MPO and vitamin D deficiency and insufficiency to deviate our conclusions." (PMID 35983482, 2022). "Besides, in a sensitivity analysis exploring elevated MPO and vitamin D deficiency and insufficiency, we assessed unmeasured confounding by calculating E value." (PMID 35983482, 2022). "The results showed that it is unlikely that any unmeasured confounders could explain the association between elevated MPO and vitamin D deficiency/insufficiency." (PMID 35983482, 2022).
vitiligo (2 papers, 2019 to 2024). Generalized well circumscribed patches of leukoderma that are generally distributed over symmetric body locations and is due to autoimmune destruction of melanocytes. "The five key target genes (AKT1, VEGFA, ESR1, IL2, and MPO) identified by the compound–target network were closely related to the pathogenesis and/or treatment of vitiligo." (PMID 38659590, 2024). "Moreover, KBL was found to modulate vitiligo via the regulation of activity of multiple series enzymes such as tyrosinase (TYR), oxidoreductase (GSTP1, CAT, MPO, and GSTM1), and controlling signal transducer (NFE2L2)." (PMID 31781265, 2019).
acute suppurative otitis media (1 paper, 2013). "In bacterial acute suppurative otitis media, production of the MPO-mediated oxidant HOCl in leukocytes and the dead bacteria can induce an inflammatory reaction that would lead to lipid peroxidation." (PMID 23756625, 2013).
alcoholic hepatitis (1 paper, 2023). Acute hepatitis resulting from ingestion of alcohol. "Comparison of serum A1AT, NE, and MPO levels in patients with ALD based on the degree of alcoholic hepatitis and mDF scores (Mann-Whitney test)a." (PMID 36607987, 2023).
Alport syndrome (1 paper, 2017). A rare renal disease characterized by glomerular nephropathy with hematuria progressing to end-stage renal disease (ESRD), frequently associated with sensorineural deafness, and occasionally with ocular anomalies. "Studies have shown an association between HLA-DQ polymorphisms and anti-myeloperoxidase ANCA vasculitis but there is as yet no gene predisposition to ANCA vasculitis linked to the X chromosome, where the locus of Alport syndrome is located." (PMID 28356090, 2017).
amyloid (1 paper, 2022). "We observed significant correlations between both amyloid and tau deposition and MPO accumulation, although this was stronger for amyloid than tau." (PMID 35331340, 2022).
anal prolapse (1 paper, 2022). "Reduces anal prolapse, surrounding hyperemia by decreasing MPO activity, serum IL-1β, IL-6, TNF-α levels, and increasing IL-4, IL-10 levels." (PMID 35548468, 2022).
anthrax (1 paper, 2020). "Azurophilic granules can also exocytose, leading to the release of MPO and defensins, which, in turn, assist with extracellular anthrax killing." (PMID 32668703, 2020). "In addition, compstatin, as well as the immunodepletion of every complement factor tested in the study, diminished anthrax and PGN-induced MPO immunoreactivity to levels of unstimulated controls." (PMID 32668703, 2020).
aplastic anemia (1 paper, 2022). Anemia resulting from bone marrow failure (aplastic or hypoplastic bone marrow). "Phenol metabolites undergo further metabolism to form catechol and hydroquinone; the latter in the BM is converted into benzoquinones due to its high myeloperoxidase level, leading to damage in BM hematopoietic stem cells and resulting in aplastic anemia." (PMID 35812844, 2022).
arterial disease (1 paper, 2022). "Taken together, these studies indicate that increased MPO activity is not necessarily characteristic of asymptomatic arterial disease, such as the vascular dysfunction reported in the present study." (PMID 35205069, 2022).
ascariasis (1 paper, 2018). An infection that is caused by the roundworm Ascaris lumbricoides, many cases of which remain asymptomatic. "Participants with ascariasis had higher median values of MPO (P‐value = 0.04) than normal children." (PMID 30133067, 2018).
aspergillosis (1 paper, 2018). Aspergillosis is an infection, growth, or allergic response caused by the Aspergillus fungus. "In lung aspergillosis mouse model, compared with untreated aspergillosis mice, expression of NLRP3 mRNA was significantly decreased in mice intraperitoneally injected with IL-37, while levels of myeloperoxidase (Mpo), CxCl2, IL-1β, IL-17A, and IFN-γ were significantly reduced." (PMID 29805973, 2018).
aspiration pneumonia (1 paper, 2017). "Resolvin E1 administration inhibited PMN infiltration and reduced MPO levels in aspiration pneumonia in mice." (PMID 28371562, 2017).
autoinflammatory syndrome (1 paper, 2023). A group of disorders of the innate immune system characterized by attacks of seemingly unprovoked inflammation without significant levels of either autoantibodies or autoreactive T cells more characteristic of autoimmune disease. "Such pathologies might include autoinflammatory syndromes such as CNO, where a co-occurrence of total MPO deficiency possibly could lead to triggering CNO disease or perhaps increase the severity of “regular CNO”, as in the patient described here." (PMID 37954595, 2023).
benign prostatic hyperplasia (1 paper, 2021). A non-cancerous nodular enlargement of the prostate gland. "PCA administration for 28 days suppressed benign prostatic hyperplasia induced by testosterone through reduction of myeloperoxidase (MPO) activity, and NO and MDA levels." (PMID 34790246, 2021).
Bovine mastitis (1 paper, 2025). INFLAMMATION of the UDDER in cows. "The onset of bovine mastitis is accompanied by exacerbated oxidative stress, characterized by dysregulated levels of oxidative biomarkers such as MPO, LDH, SOD, and MDA." (PMID 40901059, 2025).
Burkitt lymphoma (1 paper, 2023). A rare form of malignant mature B-cell non-Hodgkin lymphoma. "To determine the impact of MPO deficiency on the anticancer efficacy of DOX, we utilized an anthracycline-responsive Burkitt Lymphoma model." (PMID 37656254, 2023). "Utilizing a murine model of anthracycline-sensitive Burkitt Lymphoma, we demonstrated that MPO deficiency does not impair the anticancer efficacy of DOX." (PMID 37656254, 2023).
C. perfringens infection (1 paper, 2022). "C. perfringens infection increased the concentrations or activities of LPS, IL-6, CRP, PCT and MPO, causing a systemic inflammatory response to broilers, while the supplement of EA in diet relieved these adverse effects." (PMID 35436978, 2022).
Campylobacter enteritis (1 paper, 2018). "In conclusion, after human Campylobacter enteritis, the serum levels of MMP-8, MMP-9 and their regulators MPO, HNE and TIMP-1 are elevated as compared to the serum levels of healthy controls." (PMID 30551610, 2018).
cavernoma (1 paper, 2022). "Immunofluorescence analysis using antibodies against different NET markers showed that there were NETs in the cavernoma in the cerebellum of these Ccm3iECKO mice, but not for the wild-type controls, as seen for Ly6g and MPO (neutrophil marker) and citrulline histone H3." (PMID 35333979, 2022). "Clusters of NETs (i.e., DAPI+MPO+CitH3+ +) can be seen for sporadic CCM in the proximity of the endothelium of cavernoma, but not for the healthy control, similar to what was seen for the Ccm3iECKO mice." (PMID 35333979, 2022).
central retinal artery occlusion (1 paper, 2020). "We report a case of central retinal artery occlusion (CRAO) accompanied by choroidal folds in a patient positive for myeloperoxidase (MPO)-antineutrophil cytoplasmic antibody (ANCA)." (PMID 32871935, 2020).
cerebral palsy (1 paper, 2023). A group of disorders affecting the development of movement and posture, often accompanied by disturbances of sensation, perception, cognition, and behavior. "In a prior birth cohort study, we discovered associations between myeloperoxidase (MPO) and IL-8 levels in umbilical cord blood with PB, yet only IL-8 exhibited a correlation with infant cerebral palsy." (PMID 38357529, 2023).
cervical (1 paper, 2024). "The damage-associated proteins (DAMPs) generated from NETs, such as citrullinated histones H3 [H3Cit] or myeloperoxidase (MPO), may interact with Toll-like receptor 4 (TLR-4) and may contribute to the maintenance of cervical inflammation and blood-brain barrier damage." (PMID 38241272, 2024).
cervical adenocarcinoma (1 paper, 2020). An adenocarcinoma arising from the cervical epithelium. "We performed proteomics analysis on samples of cervical adenocarcinoma mucus and normal cervical mucus a nd used functional annotation to screen out differently expressed proteins relevant to immune, metabolic, cell adhesion, and other cellular processes, such as myeloperoxidase and APOA1." (PMID 33194326, 2020).
choroidal tumor (1 paper, 2015). "We report the unusual clinical course of a patient with a choroidal tumor accompanied by an elevated serum myeloperoxidase- (MPO-) ANCA titer." (PMID 25949841, 2015).
chronic endometritis (1 paper, 2025). A non-granulomatous or granulomatous chronic inflammation of the endometrium. "In this study, we discovered that NETs composed of neutrophil elastase 2 (ELA2), myeloperoxidase (MPO), and citrulline Histone H3 (citrulline R2+R8+R17; citH3), were present in the endometrium of patients with chronic endometritis." (PMID 41583494, 2025).
chronic leukemia (1 paper, 2022). A slowly progressing leukemia characterized by a clonal (malignant) proliferation of maturing and mature myeloid cells or mature lymphocytes. "We found that unlike in chronic leukemias, plasma ETs markers in ND APL patients were only slightly highly elevated relative to those in healthy subjects, while plasma MPO-DNA and CitH3 levels were elevated in IT APL patients." (PMID 35479063, 2022).
collagenous colitis (1 paper, 2023). A type of microscopic colitis of unknown etiology. "Lettesjö found an elevation of fecal myeloperoxidase in collagenous colitis (median 11.7 μg/g; Q1–Q3: 2.0–124 μg/g) compared to IBS patients (median 1.7 μg/g; Q1–Q3: 0.81–5.2 μg/g), p < 0.01, and healthy controls (median 2.5 μg/g; Q1–Q3:1.1–6.3 μg/g; p < 0.05." (PMID 37445477, 2023).
colon polyps (1 paper, 2022). "However, the comparison of MPO expression in the patient characteristics including T stage, N stage, history of colon polyps, presence of colon polyps, lymphatic invasion, perineural invasion, residual tumor, BMI, age, and sex was not statistically significant (P > 0.05)." (PMID 35912260, 2022).
colonic adenomas (1 paper, 2020). "High MPO immunopositivity is, in turn, associated with increased incidence of colonic adenomas and with microsatellite instability in adenocarcinomas." (PMID 33167555, 2020).
congenital nephrotic syndrome (1 paper, 2019). "Examination of the tubulointerstitial changes that occur in nephrectomized kidneys from children with congenital nephrotic syndrome of the Finnish type (NPHS1) during infancy has shown strong interstitial expression of myeloperoxidase (MPO)." (PMID 31362427, 2019).
cor pulmonale (1 paper, 2021). Hypertrophy and dilation of the right ventricle of the heart that is caused by pulmonary hypertension. "Similar results were obtained in patients with vs. without acute cor pulmonale (36.3 [33.5, 55.1] vs. 60.3 [36.3, 101.2] p < 0.001, 0 [0, 0.1] vs. 2.3 [0.3, 4.6] p < 0.001, and 1.3 [0.7, 8.2] vs. 5.8 [1.9, 14.4] p < 0.001 for MPO+, Cit-H3+, and MPO+ Cit-H3+ NETs, respectively)." (PMID 33708778, 2021).
cranial neuropathies (1 paper, 2026). "PR3- and MPO-ANCA-associated pachymeningitis typically presents with headache and cranial neuropathies, usually with systemic involvement." (PMID 42062638, 2026).
cryoglobulinemia (1 paper, 2005). Cryoglobulinemia is a type of vasculitis that is caused by abnormal proteins (antibodies) in the blood called 'cryoglobulins.' At cold temperatures, these proteins become solid or gel-like, which can block blood vessels and cause a variety of health problems. "ATD-induced ANCA-positive patients more frequently had MPO-ANCA, ANA, AHA, IgM aCL, concomitant presence of both IgM and IgG aCL, IgM anti-β2 GP I, cryoglobulinemia and decreased C4." (PMID 16207324, 2005).
developmental delay (1 paper, 2024). "We describe a unique case of monozygotic triplets concordant for developmental delay, WM lesions, autoimmune manifestations, and MPO-ANCA positivity in whom we identified a de novo interstitial deletion of chromosome 18p." (PMID 39359478, 2024).
diabetic cardiomyopathy (1 paper, 2011). Diabetic cardiomyopathy is a disorder of the heart muscle in people with diabetes. "In the present study, diabetic cardiomyopathy is characterized by an decrease in the phosphorylation state of Akt and GSK-3β, which was associated with augmented cardiac inflammation as evidenced by increased NF-κB phosphorylation and TNF-α, IL-6 expression, as well as increased MPO activity." (PMID 21232147, 2011).
Disseminated intravascular coagulation (1 paper, 2018). Disseminated intravascular coagulation is characterized by the widespread activation of coagulation, which results in the intravascular formation of fibrin and ultimately thrombotic occlusion of small and midsize vessels. "Neither cf-DNA nor MPO-DNA levels were correlated with the disseminated intravascular coagulation (DIC) score or the platelet count." (PMID 30005596, 2018).
dry eye syndrome (1 paper, 2024). A syndrome characterized by dryness of the cornea and conjunctiva. "Some other symptoms also existed – rash on limbs, increased eosinophils, hyperemia in both eyes considered chronic uveitis and dry eye syndrome, and positive P-ANCA and MPO-ANCA." (PMID 39312300, 2024).
duodenitis (1 paper, 2023). Acute or chronic inflammation of the duodenum. "The duodenitis rats showed significantly higher duodenal levels of myeloperoxidase, TNF-α, IL-6, malondialdehyde, and cleaved caspase-3, a significantly lower GSH level, and histopathological alterations." (PMID 37255094, 2023). "In rats with duodenitis, the concentrations of MPO, TNF-α, IL-6, MDA, and cleaved caspase-3 significantly increased while the GSH level decreased in the duodenal homogenate." (PMID 37255094, 2023). "Effects of olmesartan medoxomil raw drug (OM) and zeinmersomes formula (OMZ) on duodenal concentrations of MPO, THF-α, IL-6, MDA, GSH, and cleaved caspase-3 in indomethacin-induced duodenitis in rats (n=8)." (PMID 37255094, 2023).